GDF11 (growth differentiation factor 11)
Diseases named in the same sentence as GDF11 in open-access papers (continued):
Sharing a sentence is not in itself a finding about the gene and the disease.
Myocardial fibrosis (4 papers, 2021 to 2025). "Immunohistochemical staining for collagenase III also demonstrated that GDF11 reduced myocardial fibrosis caused by DCM." (PMID 38715043, 2024). "In diabetic mice, GDF11 alleviated cardiomyocyte pyroptosis, reduced myocardial fibrosis, and improved cardiac function." (PMID 38715043, 2024). "GDF11 exhibits an anti-myocardial fibrosis effect in transverse aortic constriction (TAC) surgery, diabetic cardiomyopathy (DCM), and myocardial ischemia-reperfusion (MI/R) injury." (PMID 38143761, 2023). "GDF11 supplementation has been reported to diminish myocardial fibrosis in disease states." (PMID 34262905, 2021).
thalassemia (4 papers, 2022 to 2024). An inherited blood disorder characterized by a decreased synthesis of one of the polypeptide chains that form hemoglobin. "Previous research has indicated that the downregulation of GDF11 expression has been proposed as a potential treatment for thalassemia." (PMID 38611614, 2024). "It was shown that in mouse models of thalassemia, extramedullary splenic stress erythropoiesis is associated with overexpression of the TGF-β superfamily ligand GDF11." (PMID 35682828, 2022). "Increased serum GDF11 levels were also detected in thalassemia patients, confirming the data obtained in mice." (PMID 35682828, 2022).
triple-negative breast carcinoma (4 papers, 2020 to 2024). An invasive breast carcinoma which is negative for expression of estrogen receptor (ER), progesterone receptor (PR), and human epidermal growth factor receptor 2 (HER2). "This impairment stemmed from a loss of GDF11 function in the triple-negative breast cancer cells, which was associated with a disruption in maturation and secretion noted in seven cell lines." (PMID 38611614, 2024). "Moreover, the results of IHC analysis for the localization of GDF11, ER, PR, Her2/neu, and Ki67 in cancer tissues revealed a loss of GDF11 expression in the patients with triple-negative breast cancer." (PMID 38611614, 2024). "Notably, the patients with triple-negative breast cancer exhibited a loss of GDF11 expression." (PMID 38611614, 2024). "For example, GDF11 has been demonstrated to exert tumor suppression effects in some studies such as in patients with triple-negative breast cancer, but to have the opposite effect in others." (PMID 38611614, 2024). "In contrast, GDF-11 suppresses invasiveness in human liver, pancreatic, and triple-negative breast cancer cells." (PMID 35705978, 2022). "Furthermore, the signaling pathways in triple-negative breast cancer cell lines were impaired despite the increased levels of GDF11." (PMID 38611614, 2024). "Furthermore, GDF11 expression was absent in patients with triple-negative breast cancer." (PMID 38611614, 2024). "In triple-negative breast cancer (TNBC), a lack of PCSK5 could lead to the bioactivity of growth differentiation factor (GDF11) as a tumor-suppressor." (PMID 32647495, 2020).
Anorexia (3 papers, 2020 to 2022). Lack of desire to eat (loss of appetite). "Conversely, researchers from the Novartis Institute for Biomedical Research found that anorexia and muscle loss, as complications in cancer, are mainly caused by increased levels of GDF-11, with GDF-15 being upregulated in response to supraphysiologic administration of GDF-11." (PMID 32508832, 2020). "It was previously reported that young mice, where GDF11 was supraphysiologically expressed through plasmid insertion into the liver, lost weight due to anorexia and GDF15 activation, and displayed signs of frailty." (PMID 31637864, 2020). "Blockade of GDF-11 prevented both anorexia and muscle loss, whereas inhibition of GDF-15 was most effective against anorexia." (PMID 32508832, 2020). "However, the finding that loss of muscle mass depends on GDF-11, whereas GDF-15 is mainly responsible for anorexia, would seem to indicate that such drugs would be of limited usefulness in cancer patients with wasting syndrome." (PMID 32508832, 2020). "Together with the fact that no anorexia was observed, these results suggest that GDF11 induces a healthy, GDF15‐independent weight loss in aged mice." (PMID 31637864, 2020). "Tumour-driven cytokines, such as growth differentiation factor 11, IL-1β, IL-6 leukaemiaia inhibitory factor, TNF-α, and TGFβ1 promote cancer cachexia with anorexia in the brain, proteolysis in the skeletal muscles, and browning in the WAT." (PMID 35406121, 2022).
Atrophy (3 papers, 2017 to 2025). Any weakening or degeneration, especially through lack of use. "Although they have shown that their antibody has the capacity to increase muscle mass in vivo using a steroid-mediated atrophy mouse model, they did not compare the effects of their antibody with those of anti-mature myostatin antibodies that have GDF11 cross-reactivity." (PMID 33495503, 2021).
colorectal cancer (3 papers, 2022 to 2025). A primary or metastatic malignant neoplasm that affects the colon or rectum. "Patients with colorectal cancer and high tumor expressions of GDF11 often have high rates of lymph node metastasis and poor survival." (PMID 38611614, 2024). "Among target genes, GDF11 has been shown to play a key role in diverse diseases, such as cardiovascular disease, acute pancreatitis, and colorectal cancer." (PMID 35978818, 2022).
left ventricular hypertrophy (3 papers, 2020 to 2023). Enlargement of the LEFT VENTRICLE of the heart. "In humans, lower levels of GDF11 have been linked to left ventricular hypertrophy and restoration of GDF11 levels reverses age-related cardiac hypertrophy in mice." (PMID 37163425, 2023). "In the Heart and Soul study, GDF11 levels decreased in older participants, while the levels of GDF11 were associated with left ventricular hypertrophy and cardiovascular outcomes (e.g., death)." (PMID 33886503, 2021).
myocardial ischemia (3 papers, 2020 to 2021). A disorder of cardiac function caused by insufficient blood flow to the muscle tissue of the heart. "It has been reported that growth differentiation factor 11 (GDF11) protects against myocardial ischemia/reperfusion (IR) injury, but the underlying mechanisms have not been fully clarified." (PMID 34215721, 2021). "Additional evidence and clarification of the potential mechanisms underlying the role of GDF11 in myocardial ischemia would be helpful for identifying new therapeutic targets." (PMID 34215721, 2021). "Although limited by a small sample size, data from this study support the protective effects of myocardial ischemia-reperfusion injury of GDF11 through activation of telomerase in animal models." (PMID 34215721, 2021). "To date, only a few reports have demonstrated the cardioprotective effects of GDF11 on myocardial ischemia." (PMID 34215721, 2021).
non-alcoholic fatty liver disease (3 papers, 2019 to 2022). "The association of circulating concentrations of GDF11 with the AST/ALT ratio suggests that this factor may be involved in the development of non-alcoholic fatty liver disease." (PMID 30897065, 2019). "We evaluated the role of GDF11 in healthy conditions and in the transition from non-alcoholic fatty liver disease (NAFLD) to non-alcoholic steatohepatitis (NASH)." (PMID 33126224, 2020).
psoriasis (3 papers, 2020 to 2025). An autoimmune condition characterized by red, well-delineated plaques with silvery scales that are usually on the extensor surfaces and scalp. "In this context, recent scientific studies have demonstrated the anti-inflammatory effects of Growth Differentiation Factor 11 (GDF11) in different experimental models of inflammatory diseases such as arthritis, psoriasis, and Ulcerative Colitis." (PMID 37138633, 2023). "As the key member of the TGF-β superfamily, GDF11 represents a promising therapeutic agent for the treatment of a number of inflammatory skin diseases, including psoriasis." (PMID 32283613, 2020). "According to recent studies, GDF11 may represent a promising target for the prevention and treatment of psoriasis-like skin." (PMID 32283613, 2020). "In a study reporting the role of GDF11 in inhibiting the inflammatory process on mice skin similar to psoriasis, the attenuation of the disease could be attributed to blockage of NF-κB signalization pathway, being reported low levels of expression when rGDF11 was administered i.p.." (PMID 37138633, 2023). "Researches reveal that Growth Differentiation Factor 11 (GDF11), part of the TGF-β superfamily, eases skin inflammation in a mouse model of psoriasis induced by imiquimod." (PMID 40303401, 2025).
Arthritis (2 papers, 2021 to 2023). Inflammation of a joint. "Another study showed that GDF11 inhibited the expression of MMP‐3 in the collagen‐induced arthritis." (PMID 33764670, 2021).
Cerebral ischemia (2 papers, 2023 to 2025). Restriction of arterial blood supply to the brain associated with insufficient oxygenation to support the metabolic requirements of the tissue. "After cerebral ischemia, IF pretreatment has been demonstrated to improve the nervous system, potentially in the form of growth differentiation factor 11 (GDF11)/activin-like kinase 5 (ALK5) signaling." (PMID 40259102, 2025). "Our previous research has suggested that GDF11 is an angiogenic factor following cerebral ischemia (CI)." (PMID 36996042, 2023).
cognitive decline (2 papers, 2015 to 2023). "Here, the authors show that GDF11 in ENs slows EN senescence, brain ageing, cognitive decline and maintains lifespan, revealing a mechanism underlying EN senescence and brain ageing." (PMID 37978295, 2023). "Collectively, both focal and systemic deletion of GDF11 in the EN deteriorates sociability, social memory and object recognition memory in mice, indicating that induction of cellular senescence in the EN by deleting GDF11 is sufficient to cause cognitive decline." (PMID 37978295, 2023). "Moreover, GDF11 deletion-induced EN senescence, which requires p21, is sufficient to accelerate brain ageing, cause cognitive decline and shorten lifespan." (PMID 37978295, 2023). "This implied that the elevated systemic GDF11 level in old AD mice might contribute to the ameliorative effect on cognitive decline." (PMID 26317549, 2015).
colitis (2 papers, 2019 to 2024). Inflammation of the colon. "It has been reported that GDF11 can ameliorate experimental colitis by inhibiting NLRP3 inflammasome activation." (PMID 38715043, 2024). "In addition, GDF11, by inhibiting the NLRP3 inflammasome activation evidenced in vivo and in vitro, ameliorates experimental colitis in mice." (PMID 31248139, 2019).
colon cancer (2 papers, 2015 to 2023). "Notably, GDF11 is associated with human colon cancers, which is likely due to the pro-angiogenic properties of GDF11 and most TGF-beta family ligands." (PMID 26540176, 2015). "Therefore, we categorized the tested lung and colon cancer cell lines in two groups depending on GDF15 reduction and GDF11 induction upon BET inhibition and explored differences in protein expression, gene dependency, drug sensitivity and metabolites." (PMID 37495707, 2023).
diabetic cardiomyopathy (2 papers, 2021 to 2024). Diabetic cardiomyopathy is a disorder of the heart muscle in people with diabetes. "However, the roles and underlying mechanisms of GDF11 in diabetic cardiomyopathy (DCM) remain largely unknown." (PMID 34262905, 2021). "Previous studies have reported that GDF11 is involved in protecting against various cardiovascular diseases and can alleviate diabetic cardiomyopathy by inhibiting apoptosis and oxidative stress." (PMID 38715043, 2024). "However, the potential role of GDF11 in regulating cardiomyocyte pyroptosis to prevent the progression of diabetic cardiomyopathy has not been experimentally confirmed." (PMID 38715043, 2024).
fibrosis (2 papers, 2020 to 2021). the formation of excess fibrous connective tissue in an organ or tissue in a reparative or reactive process. "Even though, the small sample size constrained our ability to provide a statistically significant correlation with all fibrosis stages, our results if validate in other cohorts could reinforce the relevance of GDF11 as therapeutic target to reduce NAFLD-associated liver damage." (PMID 33126224, 2020). "In particular, a significant increase in GDF11 mRNA was observed in F1 (portal fibrosis) compared to F0 (no fibrosis)." (PMID 33126224, 2020).
Hypertension (2 papers, 2016 to 2019). The presence of chronic increased pressure in the systemic arterial system. "This analysis allowed us to identify 6 well-annotated genes: RTP4, FXYD6, GDF11, IFNAR1, NOX3, and HLA-DQ2, associated with dynamics of future hypertension incidence." (PMID 27980621, 2016). "GDF11 levels were not related to the presence of hypertension or cardiopathy." (PMID 31248139, 2019). "In the present study we have observed that GDF11 levels are not related to the presence of an anomalous ECG, hypertension, or cardiopathy." (PMID 31248139, 2019).
leukemia (2 papers, 2020 to 2025). A malignant (clonal) hematologic disorder, involving hematopoietic stem cells and characterized by the presence of primitive or atypical myeloid or lymphoid cells in the bone marrow and the blood. "Although this study provides evidence that GDF11 decreases some markers of aggressiveness in human-derived leukemia cells, it is important to note that the main limitation is the cellular model." (PMID 40746879, 2025). "Considering that GDF11 impacts poorly differentiated cells, we decided to explore the effects of this growth factor on cells derived from human leukemia." (PMID 40746879, 2025). "There is poor evidence regarding the GDF11 in the biology of leukemia cells." (PMID 40746879, 2025). "To support the idea that GDF11 could induce a cellular response tending to decrease aggressivity in the leukemia cells, we assessed the migratory and invasive capacity of the cells under GDF11 treatment using Boyden’s chambers." (PMID 40746879, 2025). "This research suggests that GDF11 could be an exciting target for further exploration in leukemia therapeutic approaches." (PMID 40746879, 2025). "In addition, iron overload has an impact on leukemia transformation and survival, and is known to be related to GDF-11, GDF-15, and hepcidin." (PMID 32344823, 2020).
liver diseases (2 papers, 2020 to 2024). "In the context of liver diseases, exogenous GDF11 expression correlates with tumor suppression in HCC cells in vitro, but worsens hepatocellular injury and liver regeneration after liver ischemia reperfusion injury in vivo." (PMID 33126224, 2020). "However, there are inconsistencies in the impacts of GDF11 analogues on liver diseases which might be due to diversity in GDF11 dosage or the methods used for increasing GDF11 (such as recombinant GDF11 or GDF11 overexpression by plasmid or viral vectors)." (PMID 38494851, 2024). "Background & aims: Growth Differentiation Factor 11 (GDF11) is an anti-aging factor, yet its role in liver diseases is not established." (PMID 33126224, 2020).
lung adenocarcinoma (2 papers, 2020 to 2023). A carcinoma that arises from the lung and is characterized by the presence of malignant glandular epithelial cells. "They reported that inhibiting GDF11 expression can effectively overcome the development of intrinsic platinum resistance in lung adenocarcinoma." (PMID 38143761, 2023).
lung fibrosis (2 papers, 2010 to 2024). "The investigation also revealed two GDF11 variants associated with “self-reported pulmonary fibrosis”: rs12304296 and rs7297523 (p = 8.69E-06 and p = 8.99E-06, respectively)." (PMID 39237910, 2024).
lymph node metastasis (2 papers, 2019 to 2024). "The classification of the patient cohort in low and high GDF11 expression revealed that those patients with high levels of GDF11 showed a higher frequency of lymph node metastasis, more deaths and lower survival." (PMID 31681577, 2019).
metabolic syndrome (2 papers, 2023 to 2024). A cluster of metabolic risk factors for CARDIOVASCULAR DISEASES and TYPE 2 DIABETES MELLITUS. "In a cohort study, GDF11 played a key role in various metabolic processes and was closely associated with metabolic syndrome in the Chinese population." (PMID 36996042, 2023).
mucositis (2 papers, 2023 to 2024). Mucositis is inflammation and damage of the mucous membranes lining the mouth and other parts of the gastrointestinal (GI) tract. "Our results showed that recombinant L. lactis (pExu:gdf11) strains were able to partially ameliorate the intestinal damage of mucositis by preventing infiltration of neutrophils, preserving goblet cells count and intestinal mucosa architecture." (PMID 37138633, 2023). "Results showed the presence of infiltrating cells in groups that received 5-FU for mucositis induction; however, mice receiving recombinant L. lactis NCDO2118 (pExu:gdf11) showed a significant decrease (p < 0.01) in MPO activity, therefore supporting the histology results." (PMID 37138633, 2023). "Regarding IBDs, GDF11 was able to ameliorate UC in a mice model through inhibition of NLRP3 inflammasome complex, the main responsible for the maturation of pro-inflammatory cytokine IL-1β and markedly present in mucositis induced by 5-FU." (PMID 37138633, 2023).
muscular dystrophies (2 papers, 2016 to 2019). "These initial findings led us to investigate the ability of GDF11 to promote regeneration in the context of muscular dystrophy and determine whether it could be a candidate to slow down or reverse the disease progression in DMD." (PMID 27303621, 2016).
oral cancer (2 papers, 2019 to 2022). "In oral cancer cells, treatment with GDF-11 stimulates cell migration and induced expressions of MMP2 and MMP9." (PMID 35705978, 2022). "In oral squamous cell carcinoma, Qin and coauthors showed that in a small patient cohort GDF11 expression is positively correlated with aggressiveness, finding a higher expression in metastatic oral cancer (n = 19) in comparison with non-metastatic oral cancer (n = 15)." (PMID 31681577, 2019).
pulmonary arterial hypertension (2 papers, 2022 to 2025). Pulmonary arterial hypertension (PAH) is a group of diseases characterized by mean pulmonary artery pressure >20 mmHg and elevated pulmonary arterial resistance leading to right heart failure. "ActRIIA-Fc functions by sequestering multiple ligands of the TGF-β superfamily, including Activins, Mstn, GDF-11, and select BMPs, and was recently approved by the FDA for the treatment of pulmonary arterial hypertension in adults (NCT04576988)." (PMID 41249489, 2025).
renal agenesis (2 papers, 2019 to 2023). Renal agenesis (RA) is a form of renal tract malformation characterized by the complete absence of development of one or both kidneys (unilateral RA or bilateral RA respectively), accompanied by absent ureter(s). "Due to the perinatal lethality of Gdf11-knockout mice, which exhibit homeotic skeletal transformations, cleft palate, and renal agenesis, the functions of GDF11 in postnatal tissues are less explored." (PMID 38235060, 2023). "In contrast, 63.6% (7 out of 11 analyzed) of Gdf11indel/indel embryos exhibited bilateral renal agenesis and 36.4% (4 out of 11 analyzed) exhibited unilateral renal agenesis, again consistent with previous results in Gdf11 knockout mice." (PMID 31819086, 2019). "4% (1 out of 25 examined) of Gdf11indel/+ embryos exhibited unilateral renal agenesis, consistent with previously reported results from Gdf11 heterozygous mice." (PMID 31819086, 2019).
renal fibrosis (2 papers, 2016 to 2022). A final common manifestation of a wide variety of chronic kidney diseases characterized by glomerulosclerosis and tubulointerstitial fibrosis. "The effect of GDF11 on renal fibrosis after AKI needs to be explored 2 weeks after IRI in the future." (PMID 27703192, 2016).